CD4 (CD4 molecule)
Diseases named in the same sentence as CD4 in open-access papers (continued):
Sharing a sentence is not in itself a finding about the gene and the disease.
Obesity (continued). "A high proportion of overweight and obesity was reported among hypertensive study participants 36 (65.5%) followed by participants whose recent CD4 counts ≥ 500 cells/mm399 (49.5%)." (PMID 35821078, 2022). "The impact of obesity on the exhaustion of CD4+ T cells, including PD-1 expression, requires further investigation." (PMID 36611881, 2022). "In a study performed on a small cohort, cord blood mononuclear cells isolated from infants born to mothers with obesity showed an increased number of CD4+ cells and reduction in myeloid cell population." (PMID 36189369, 2022). "This study also showed that CD4+ T helper cells from subjects with obesity had defects in activation and function when challenged with pH1N1 ex vivo." (PMID 36275776, 2022). "In mice fed a HFD, the absolute number of CD4 T cells per gram of VAT continues to increase as obesity progresses." (PMID 36685567, 2022). "CD8- and CD4-expressing cells also play key roles in the induction of AT inflammation in the context of obesity." (PMID 36033972, 2022). "Overweight and obesity were significantly higher among hypertensive, with higher recent CD4 counts, higher BMI at the commencement of ART and abdominal obese ART patients." (PMID 35821078, 2022). "Our results comparing larger numbers of both lean individuals with those with obesity demonstrate that Treg abundance falls by >70%, from ~20% of CD4 + cells in lean to ~5% in obesity in both VAT and SAT." (PMID 36153324, 2022). "Although obesity has been shown to be biased toward CD4+ T cell differentiation and directly affect trafficking ability, little is known about the impacts of obesity on the anti-tumor activity of CD4+ T cells." (PMID 36611881, 2022). "In humans, homeostatic proliferation of circulating CD4 T cells is accelerated in individuals with obesity." (PMID 36685567, 2022). "In comparing different levels of obesity and different Child–Pugh grades, the CD4+ T effector memory cells, immature dendritic cells, and macrophages M2 had higher scores in obese people and in the Child–Pugh grade B/C population." (PMID 35924239, 2022). "We therefore tested epigenetic adaptations of offspring CD4 T cells in response to pregravid obesity using bisulfite sequencing and chromatin accessibility profiling." (PMID 33912153, 2021). "The percentage of CD4+IL-17+ T cells in adipose tissue increased with obesity, and the percentage of CD4+IL-17+ cells in the spleen was higher in obese mice (60% kcal fat, 10 weeks) compared with control mice." (PMID 33670988, 2021). "Despite their similar degree of obesity, they differed by more than twofold higher basophil levels in the Dercum’s group and a significantly lower CD 3+ and CD4+ & CD8+ T lymphocytes subpopulations levels in the LMS group." (PMID 34187516, 2021). "Here, we provide an overview of the biology of macrophages in adipose tissue and the relationship between other immune cells, such as CD4+ T cells, natural killer cells, and innate lymphoid cells, and obesity and type 2 diabetes." (PMID 34576181, 2021). "The present study’s main aim is to investigate the alterations of the immune phenotype of CD4+ T-lymphocyte subpopulations in class III obesity undertaking bariatric surgery and after 12 weeks of the intervention." (PMID 33981153, 2021). "have reported an association between pre-ART BMI and 12-month change in CD4-cell counts (P-value < 0.001) and concluded that a BMI indicative of threshold obesity predicted greater CD4-cell count gains at the beginning of ART46." (PMID 34155234, 2021). "To address the contribution of diet-induced obesity to the functional characteristics of lymphocytes, we measured the populations of pro-inflammatory cytokine-producing CD4+ and CD8+ T cells in the regional lymph nodes of mice fed either a NCD or a HFD." (PMID 35069547, 2021). "Obesity impaired the ability of both CD4+ and CD8+ TILs to mount productive and sustained effector responses." (PMID 34064933, 2021).
Obesity (continued). "For instance, accumulation of CD4+ T cells which are Th1 cells in adipose tissue preceded the recruitment of macrophages during the development of obesity and IR in mice." (PMID 34091599, 2021). "This enhanced CD4+ population in people with obesity is composed mainly of T naïve, T central memory, and Th2 cells." (PMID 34445165, 2021). "In this study, we collected umbilical cord blood samples from infants born to lean mothers and mothers with obesity and profiled CD4 T cells using flow cytometry and single cell RNA sequencing at resting and following ex vivo polyclonal stimulation." (PMID 33912153, 2021). "Specifically, loci associated with T cell activation (CD3, CD28) were hypomethylated in cord blood CD4 T cells from babies born to mothers with obesity." (PMID 33912153, 2021). "The comparative Treg number among CD4+ T cells was much higher than in other tissues of healthy individuals, and the number decreases in obesity." (PMID 33413697, 2021). "In conclusion, ex vivo-generated CD4+ T cell cDNT exert potent protection against diet-induced obesity, type 2 diabetes, and NASH." (PMID 33510172, 2021). "Recent studies have demonstrated that obesity selectively stimulate the secretion of IL-17 producing CD4 + T (Th17) cells in adipose tissues, aggravating autoimmune response in mice model." (PMID 34176464, 2021). "In this study, we investigate the molecular basis by which obesity and leptin signaling mediates CD4+ T cell expansion and effector responses in vitro." (PMID 35111163, 2021). "Recent work in rodent models of HFD-induced obesity links dietary fat and metabolic stress with biased memory CD4 T cell differentiation in adipose and vascular tissue in a PI3K-Akt dependent manner." (PMID 33912153, 2021). "In the present study, we used a mouse model of HFD-induced obesity to study the relationship(s) between adipocytes, both CD4+, CD8+ T cells, CXCR3 expression, and macrophage function in the obese AT microenvironment." (PMID 34248964, 2021). "Mice with high fat diet (HFD)-induced obesity have also been reported to present an increased number of macrophages, CD4+, and CD8+ T cells in adipose tissue, along with augmented expression of IFN-γ mRNA and IFN-γ secretion when compared with lean mice." (PMID 34108550, 2021). "Regarding the impact of obesity on CD4 T cell reconstitution, patients with higher BMI before ART initiation exhibit higher or comparable immune reconstitution." (PMID 34220817, 2021). "Evaluation of immune cell subsets showed HFD-induced obesity drove the upregulation of activated NK cell-activating receptor (NKp46)+ NK cells and pro-inflammatory macrophages (MHCIIhigh Mφ) as well as CD4+ and CD8+ T cells in the normal pregnancy group." (PMID 34177956, 2021). "Epidemiological studies demonstrate that obesity, or a body mass index (BMI) ≥ 30 kg/m2, is positively correlated with greater CD4+ T cell recovery in PLWH on ART." (PMID 35111163, 2021). "Many similarities in chronic inflammation in adipose tissue have been identified between obesity and aging, such as an increase number of CD4+ or CD8+ T cells and a decreased amount of iNK T cells." (PMID 33748126, 2021). "We report increased relative frequency of transitional effector memory and effector memory CD4 T cells in cord blood of babies born to mothers with obesity." (PMID 33912153, 2021). "Cytokine production by T cells remained essentially unchanged with pregnancy and pregravid obesity except for enhanced Th2 responses (IL-4+ CD4 T cells)." (PMID 34195568, 2021). "As afore‐mentioned, there is a positive correlation between circulating CD4+T cells and elevated BMI or obesity." (PMID 33332766, 2021). "In this study, we showed that pre-gravid obesity upregulated CD4+ or CD8+ T cell frequencies in NP while downregulated T lymphocyte abundance in AP mouse models." (PMID 34177956, 2021).
Obesity (continued). "CD4+ T cells are critical for sustaining CD8+ cytotoxic T cell immunity, and our results here suggest that closer attention should be paid to CD4+ T cell immune responses following immunotherapy administration, particularly in the context of obesity." (PMID 34064933, 2021). "Elevated fatty acid levels promote the differentiation of CD4+ T cells toward an effector-memory-like phenotype in obesity and suppress the NK cell-mediated anti-tumor response through the accumulation of intracellular lipids." (PMID 33170123, 2020). "Despite the small sample size, this finding indicates that CD4+ICOS+ T cells play an important role in affecting the efficacy of immunotherapy in obesity." (PMID 32212417, 2020). "CD4 T cells producing the CD4 molecule was proved to play a positive role not only in obesity and insulin resistance development, but also in the obesity memory of previous obesity, since their depletion resulted in the loss of this memory." (PMID 32899471, 2020). "Specifically, infiltration of CD8+ and inflammatory CD4+ T cells into adipose tissue is increased with obesity, while CD4+ Tregs are reduced, contributing to adipose tissue inflammation and insulin resistance." (PMID 33170123, 2020). "Adaptive immunity is also disrupted in obesity, with a sharply decrease in anti-inflammatory CD4+ and CD8+ cells and an increased percentage of proinflammatory immune cells such as Th17 and Th22 cells." (PMID 33267871, 2020). "Additionally, CD4+ T cells play an important role in mediating crosstalk between immune cells and adipose tissues with an increase in adipose tissues known to be associated with obesity and obesity-associated diseases, including type 2 diabetes, insulin resistance, atherosclerosis, and stroke." (PMID 33383959, 2020). "Underweight patients had the lowest median CD4 cell count, followed by recipients with normal BMI, while patients with overweight/obesity had the highest median CD4 cell count (p < 0.030)." (PMID 32395339, 2020). "In fact, Th1 cells are similar in proportion to Tregs in lean conditions, while they occur at a higher frequency in comparison to other CD4+ cell subtypes in obesity." (PMID 33282920, 2020). "Those authors found that with obesity, PD-L1 expression decreased in renal tumors, but the frequencies of CD4+ or CD8+ T cells, B cells, and regulatory T cells were unaltered." (PMID 32469992, 2020). "Diet-induced obesity CD4+ T lymphocytes were found to have biased T cell receptor (TCR) repertoires, suggesting an antigen-specific expansion." (PMID 32581740, 2020). "CD4 is a cell surface glycoprotein produced by CD4 cells, which contributes to the development of obesity-induced inflammation, and consequently, insulin resistance in mice." (PMID 32899471, 2020). "CD4+ T cells represent the more abundant subtype in visceral AT and are further enriched in obesity." (PMID 33282920, 2020). "These cells represent approximately half of the CD4+ T-cell compartment in AT of lean mice, and it has been reported that obesity decreases their number, leading to AT inflammation and IR." (PMID 32973799, 2020). "The MHCII molecules are expressed in adipocytes and their expressions are upregulated during obesity, providing the first signal for CD4+ T cell activation." (PMID 33329579, 2020). "Palmitate, specifically, has been shown to promote T CD4+ effector memory cell differentiation in obesity." (PMID 31885787, 2019). "The linkage between ART, obesity, CD4+ T cells and elevated levels of inflammatory markers which are also adversely correlated with progression of HIV disease is known." (PMID 31479472, 2019). "Mechanistic studies on the bias toward Th17 differentiation in obesity implicated Acetyl-CoA carboxylase 1 (ACC1), which activates fatty acid synthesis in memory CD4+ T cells and controls the transcriptional activity of RORγt to activate IL-17 gene expression." (PMID 31379820, 2019).
Obesity (continued). "CD4+ Th1 cells increase in human subcutaneous adipose tissue with obesity and exhibit an activated CD25+ phenotype." (PMID 31130916, 2019). "Obesity increased the activation of CD4 and CD8+ T cells and this activation status was positively correlated with body weight, adipose tissue weight, fasting plasma glucose, and HOMA-IR." (PMID 31736971, 2019). "Obesity (p=0.047; OR=8.72; CI (95%)=1.07-39.21) and CD4 count < 200/mm3 (p=0.000; OR=58.50; IC (95%)=10.31-55.12) were associated with poor prognosis of ARF." (PMID 31762871, 2019). "Data presented here demonstrate that Foxo1 and Foxo3 in CD4+ T cells likely act as a metabolic regulator that can suppress beiging with the potential capacity to accelerate obesity-induced insulin resistance." (PMID 31756626, 2019). "In humans, obesity and T2D induce the expansion of pro-inflammatory T cells such as CD4 (Th1, Th17) and CD8 populations, whereas innate T cells such as invariant natural killer T cells and mucosal-associated invariant T cells were found reduced." (PMID 31681285, 2019). "In our study, RED extract consumption feebly ameliorated the ratio of CD8/CD4 T cells normally higher in obesity." (PMID 31337415, 2019). "Together, these results point to an important role for adiponectin in regulating CD4+ T cell inflammation in obesity." (PMID 31736971, 2019). "Anti-obesity effects of Th2s were indicated by CD4+ T cell transfer into Rag1−/− diet-induced obese (DIO) mice, which prevented weight gain and improved insulin sensitivity as a likely outcome of increased (STAT6-dependent) Th2s." (PMID 31379820, 2019). "In MGAT of HFD-fed mice, we found 3.4X IL-17A-expressing CD4+ T cells compared to MGAT of ND-fed mice, paralleling what is observed in the subcutaneous adipose tissue of patients with obesity-associated T2D." (PMID 31015794, 2019). "As with CD4+, obesity also increases CD8+ T cell levels along with their products, granzyme B and IFN-γ." (PMID 31130916, 2019). "In agreement with our results, many studies showed a positive correlation between CD4+ effector memory cells and pro-inflammatory conditions, such as aging and atherosclerosis, confirming that obesity and inflammation are strictly related." (PMID 29758052, 2018). "Another report showed that the preadipocyte- and endothelial cell-derived stromal-derived factor-1α (CXCL12), mediated early infiltration of CD4+ T lymphocytes in obesity, which preceded the increase of macrophages in adipose tissue of mice on HFD." (PMID 30619305, 2018). "MHCII in M2 macrophages is required to translate obesogenic cues into CD4+ T cell immune responses at the initial stage of obesity." (PMID 30233575, 2018). "Both conventional CD4+ T cells and CD8+ T cells are significantly increased, with a greater increase in CD8+ than CD4+ T cells, in visceral fat of aged mice compared to that of young mice, which is also similar to the change with obesity." (PMID 30619305, 2018). "CD4+ T-cells accumulate within human subcutaneous adipose tissue with obesity, exhibiting an activated CD25+ phenotype." (PMID 29479350, 2018). "Recent findings suggest that circulating CD4+ T-cells adopt an effector memory (CXCR-3+CD62L−) phenotype with human obesity in response to a metabolically driven adaptation within T-cells via the p110δ subunit of phosphoinositide 3-kinase (PI3K)." (PMID 29479350, 2018). "While accumulative studies have demonstrated a critical role of CD4+ T cells in obesity-induced inflammation, their roles in adaptive thermogenesis in subcutaneous WAT (SAT) and brown adipose tissue (BAT) remain in its infancy." (PMID 30233575, 2018). "Obesity has also been shown to stimulate expression of MHC class II on adipocytes and an activation of CD4 + T-cells, causing adipose tissue inflammation." (PMID 30250206, 2018). "Infiltration of proinflammatory CD4+ T cells into VAT is now recognized as one of the primary events in obesity-induced chronic inflammation." (PMID 30233575, 2018).
Obesity (continued). "Recent literature reports have suggested the development of biased effector memory CD4 T cell differentiation characterized by increased CD44 under obesity-induced metabolic stress." (PMID 30134638, 2018). "It has also been reported that CD4 + T-cells are involved in the pathogenesis of obesity and insulin resistance." (PMID 30250206, 2018). "During obesity, bioactive lipids released by adipocytes also involve in the regulation of CD4+ T cells." (PMID 30233575, 2018). "CD4+ T-cells within the visceral adipose tissue of obese mice display an “aged” phenotype and accumulate 4-fold with obesity." (PMID 29479350, 2018). "Regulatory T-cells represent more than half of all CD4+ T-cells in lean murine adipose tissue, and in obesity, regulatory T-cells accumulate around macrophages, produce IL-4 and IL-10, and promote Th-2 T-cell polarisation." (PMID 29479350, 2018). "In this review, we have summarized recent advances in understanding the characteristics and functional roles of AT CD4+ T cell subsets during obesity and energy expenditure." (PMID 30233575, 2018). "A large body of evidence indicates a pathological role of CD4+ T cells in obesity and insulin resistance." (PMID 30356025, 2018). "Most studies have focused on the direct relationship between macrophages and obesity, meanwhile, important questions concerning the relationship between obesity, insulin, and CD4+ T cell type populations and plastic changes among them remain unaddressed." (PMID 28651594, 2017). "Obesity for donor is also related to CD4+ T cell–mediated aGVHD of recipients by controlling the differentiation of CD4+IL-2+, CD4+IFN-γ+ and CD4+TNF-α+ and Th17 cells." (PMID 29088831, 2017). "Increasing evidence suggests a pathological role for CD4+ T cells in obesity and insulin resistance." (PMID 28251163, 2017). "Reduced CD4 cells count is an index of suppressed immunity and, expectedly CD4 cells should increase with normal weight and obesity, but decline with underweight." (PMID 29610642, 2017). "Specifically, reduced percentages of CD4(+)Foxp3(+) Treg cells were found in the abdominal fat of mice with genetic or diet-induced obesity." (PMID 27851820, 2016). "Obesity increases the accumulation of pro-inflammatory immune cells (e.g., macrophages, cytotoxic T cells and Th1 cells), while decreasing Foxp3+CD4+ Treg cells." (PMID 29051427, 2016). "Older age (≥50 years), male gender, overweight and obesity, CD4+ T-cell count (≥500 cells/μL), and WHO clinical disease stage I were all significantly associated with higher prevalence of hypertension." (PMID 27872756, 2016). "Chronic inflammation produced by obesity plays a key role in T2D development with altered immune cell populations (e.g., CD4+ Tregs) and insulin resistance contributing to the disease development." (PMID 29051427, 2016). "Obesity induced by HFD increased the CD8+/CD4+ ratio (p<0.001) in blood compared to SD, but this was only slightly reduced by B. pseudocatenulatum CECT 7765 administration (p = 0.172)." (PMID 26161548, 2015). "In the small intestine, obesity induced by the HFD slightly increased the CD8+/CD4+ ratio (p = 0.069) while this trend was slightly changed by the bifidobacteria administration, but the differences were not statistically significant." (PMID 26161548, 2015). "Among HIV-infected men, correlates of obesity included black or African American race/ethnicity, annual income >$20,000 and <$50,000, heterosexual orientation, and geometric mean CD4+ T-lymphocyte cell count >200 cells/μL." (PMID 26166086, 2015). "Our study first identified a notably expanded peripheral Th22 population (defined as CD4+ IFN-γ−IL-17−IL-22+) in both obesity and T2D patients as compared with healthy donors." (PMID 24465695, 2014). "Adipose tissue macrophages (ATM) are primary contributors to obesity-related inflammation and the derived insulin resistance, but their effector function is suppressed by CD4+CD25+Foxp3+ regulatory T cells (Treg)." (PMID 23166823, 2012).